EGR1 (early growth response 1)
Diseases named in the same sentence as EGR1 in open-access papers (continued):
Sharing a sentence is not in itself a finding about the gene and the disease.
synovial sarcoma (15 papers, 2011 to 2024). "Romidepsin (FK228), a HDAC inhibitor, reactivated EGR1 expression and caused tumor shrinkage in a preclinical synovial sarcoma model, presumably by disrupting the interactions within this complex." (PMID 23110793, 2012). "In accordance with this, expression of Atf2 and Tle1 was increased, while that of Egr1 was suppressed in mouse synovial sarcoma." (PMID 32019274, 2020). "EGR1 is repressed by the SS18-SSX fusion protein in synovial sarcoma in that SS18-SSX recruits PcG proteins, including EZH2 and Bmi1, to the EGR1 promoter and correlates with H3K27me338." (PMID 27125524, 2016). "They investigated the correlation between EGR1 and miR-183, which is significantly overexpressed in synovial sarcoma." (PMID 25165708, 2014). "Specifically, SYT-SSX2 represses the expression of the tumor suppressor gene early growth response 1 (EGR1), a regulator of cell cycle, engaging EZH2 on the EGR1 promoter in synovial sarcoma cells." (PMID 21609503, 2011). "EGR1 repression has been found to be associated with H3K27 trimethylation, and EZH2 and the PRC1 component BMI1 have been shown to directly bind its promoter, thus supporting the existence of a novel epigenetic mechanism of oncogenesis in synovial sarcoma." (PMID 21609503, 2011). "Upregulation of ATF2 and TLE1 is important in the development of human synovial sarcoma and recruitment of TLE1 to the ATF2 binding locus downregulates expression of the tumor suppressor EGR1." (PMID 32019274, 2020). "HDAC inhibitors dissociate the driving complex and reactivate EGR1 and p16INK4a/p14ARF (CDKN2A) expression in synovial sarcoma; we confirm this occurs with treatment by quisinostat, a newer HDAC inhibitor that was the top hit in our compound screen." (PMID 28056055, 2017). "EGR1 is a direct target of SS18-SSX and its transcription level is negatively correlated with SS18-SSX activity in synovial sarcoma cells." (PMID 39045458, 2024). "Chromatin immunoprecipitation revealed a decrease in HDAC1 and H3K23me3 at the EGR1 promoter, a known target for repression by the SS18-SSX/TLE1/ATF2 complex consistent with a disruption of the biologic effects on SS18-SSX target genes in synovial sarcoma." (PMID 27120803, 2016).
bladder cancer (14 papers, 2009 to 2024). "EGR1-regulated ALOX5 deficiency can promote ferroptosis resistance in bladder cancer." (PMID 39544949, 2024). "Protein expression of ERCC1, 2, and 5 was up-regulated in bladder cancer tissues and EGR1 was down-regulated in cancer tissues compared to normal bladder samples." (PMID 39192988, 2024). "Compared with normal bladder samples, the protein expression of PLOD1, ATP6V1B1, HSD17B1, SERPINB7, and PYCR1 in bladder cancer tissues was upregulated, while EGR1 in cancer tissues was down-regulated." (PMID 37880682, 2023). "MiR-301b has been shown to promote the proliferation, migration and aggressiveness of human bladder cancer cells by targeting EGR1 or through FAK and Akt phosphorylation by regulating PTEN." (PMID 30081934, 2018). "The results confirm that the induction of apoptosis by sanguinarine occurs in an Egr-1-dependent manner and that an increase in ROS generation is required for activation of Egr-1 and the occurrence of sanguinarine-induced apoptosis in bladder cancer cells." (PMID 23717422, 2013). "Although the reduction in PARP degradation was only partial, the results indicated that Egr-1 plays an important role as a gene regulator in the apoptosis of bladder cancer cells treated with sanguinarine." (PMID 23717422, 2013). "Egr-1 has also been proposed to be an early biomarker in rat urinary bladder cancer induced by dual-acting PPAR agonists." (PMID 19878561, 2009). "The frequency of tumor cells with nuclear Egr-1 immunolabelling correlated to bladder cancer stage, grade and to later progression to muscle-invasive bladder cancer (T2-4)." (PMID 19878561, 2009). "Egr-1 (early growth response-1 transcription factor) has been proposed to be involved in invasion and metastasis processes of human bladder cancer, but Egr-1 protein expression levels in human bladder cancer have not been investigated." (PMID 19878561, 2009). "Expression of Egr-1 protein in human bladder cancer was examined by immunohistochemistry, on a tissue microarray constructed from tumors from 289 patients with non-muscle invasive urothelial bladder cancer." (PMID 19878561, 2009). "In the present study we investigated the expression levels of Egr-1 protein in early stages of human bladder cancer and correlated it to later progression." (PMID 19878561, 2009). "Our study strengthens the role of Egr-1 as a mediator of transformation to invasive bladder cancers." (PMID 19878561, 2009). "Finally, transwell and wound-healing assay indicated that EGR1 inhibited the capacity of migration in bladder cancer cells." (PMID 35982887, 2022). "Therefore, the current study evaluated the involvement of Egr-1 in ROS-dependent apoptosis of bladder cancer cells by sanguinarine." (PMID 23717422, 2013). "Also the HYAL-1 hyaluronidase expression in bladder cancer has been suggested to be regulated by binding of Egr-1 to the methylated promoter of HYAL-1 hyaluronidase." (PMID 19878561, 2009). "Our study supports a role of Egr-1 in the early steps of human bladder carcinogenesis, with progression from non-muscle invasive tumors to muscle invasive cancers, and emphasizes the need for more comprehensive studies to explore the involvement of Egr-1 in human bladder cancer." (PMID 19878561, 2009). "As an adaptor, WDR4 binds DDX20 and represses the transcription factor Egr1, thereby inhibiting the transcriptional expression of ARRB2 and ultimately promoting the progression of bladder cancer." (PMID 37783676, 2023). "LPA activated AP-1, NF-κB, and Egr-1, upregulated RON expression, and thus, promoted T24 bladder cancer cells’ invasiveness." (PMID 31906413, 2020). "A role for Egr-1 in human bladder cancer progression would be expected from the fact that Egr-1 regulates heparanase and HYAL-1 hyaluronidase expression in human bladder cancer cells." (PMID 19878561, 2009).
bladder cancer (continued). "Egr-1 (early growth response factor 1, Zif268, NGFI-A, TIS8, Krox-24) has been proposed to be involved in the invasion and metastasis processes of human bladder cancer." (PMID 19878561, 2009).
ischemia (14 papers, 2008 to 2024). A hypoperfusion of the BLOOD through an organ or tissue caused by a PATHOLOGIC CONSTRICTION or obstruction of its BLOOD VESSELS, or an absence of BLOOD CIRCULATION. "Egr-1 has been linked with atherogenesis, myocardial ischemia-reperfusion injury, cardiac fibrosis and heart failure." (PMID 39619154, 2024). "The aberrant expression of EGR1 is associated with the disease of ischemia, and previous research showed that it was upregulated in the surroundings of hypoxia." (PMID 37108043, 2023). "Early growth response-1 (Egr-1) is a transcriptional factor upregulated in response to ischemia and reperfusion, and initiates the expression of chemokines, adhesion molecules, and coagulant factors." (PMID 35631325, 2022). "Thereby, with the beneficial effect in rats with either inferior caval vein occlusion or bilateral carotid artery occlusion, there is increased Egr1 expression, which is relevant for both, but especially so in the ischemia/reperfusion stroke rats." (PMID 32558293, 2020). "In order to determine the role of Egr1 in ischemia-induced blood flow recovery in vivo, we over-expressed Egr1 in the hind limb of mice by using an Erg1 expressing adenoviral vector." (PMID 31530804, 2019). "Collectively, the data indicates that Egr1 regulates the expression of multiple growth factors involved in blood flow recovery from ischemia." (PMID 31530804, 2019). "Foxo3a then translocates to the nucleus where it mediates suppression of Egr1/Creb1, the transcriptional regulators of multiple pro-angiogenic growth factors, mitigating recovery from ischemia." (PMID 31530804, 2019). "Egr-1 functions as a master switch activated by ischemia to trigger expression of pivotal regulators of inflammation, coagulation and vascular hyperpermeability." (PMID 25897838, 2015). "All of those genes, which were upregulated after IONT and IONC, are also upregulated after ischemia, retinal scraping, experimental glaucoma, and phototoxic lesions (in the case of Egr1)." (PMID 18552980, 2008). "Thus, the data from this study indicates that neural Egr1 and Creb1 are important modulators of the vascular response to ischemia and mediate, in part, ischemic blood flow recovery in the hind limb." (PMID 31530804, 2019). "Thus, JNK3 deficiency improves blood flow recovery by allowing full activity of Egr1/Creb1 to promote neuronal growth factor expression that contributes to the revascularization response to ischemia." (PMID 31530804, 2019). "However, EGR1 expression is also increased by volutrauma in the adult rat lung and it plays a pivotal role in the response to pulmonary ischaemia-reperfusion injury in the adult mouse." (PMID 19284536, 2009). "While EGR-1 was already a recognized CO-target, the finding that CO-suppresses multiple family members suggests a more general role in regulating vascular inflammation due to ischemia." (PMID 19956541, 2009). "Additionally, redox signaling may have an impact on genes that regulate inflammation, such as Early growth response-1 (Egr-1), and a reduction in Egr-1 gene expression may lessen ischemia damage and provide cardioprotection." (PMID 36829584, 2023). "Moreover, the expression of Egr1 and Egr3 was induced by ischemia." (PMID 24886494, 2014). "Therefore, in the absence of JNK3, Foxo3a is trapped in the cytoplasm and Egr1/Creb1 promote uninhibited transcription of multiple growth factors that enhance blood flow recovery from ischemia." (PMID 31530804, 2019).
liver cancer (14 papers, 2015 to 2025). An epithelial or non-epithelial malignant neoplasm that arises from the liver. "Previous studies have shown that EGR1, a tumor suppressor gene, plays a role in inhibiting tumor cell glycolysis in liver cancer." (PMID 39044249, 2024). "The role of Egr1 in liver cancers remains elusive, as studies evaluating the role of Egr1 in liver cancer development and progression have reported contradicting conclusions." (PMID 29607419, 2017). "The purpose of this review is to summarize current studies pertaining to the role of Egr1 in liver metabolism and liver diseases including liver cancer." (PMID 29607419, 2017). "Improving our understanding of Egr1 in liver metabolism and liver cancer may provide new insights to facilitate developing novel treatments or prevention strategies for liver diseases." (PMID 29607419, 2017). "To explore whether mature miR675 alters EGR1 expression, we consider to reveal whether mature miR675 impacts on the Histone 3 modification in liver cancer cells." (PMID 26376677, 2015). "Thus, it could be interesting to know whether the same mechanism could exist in liver cancer and contribute to the decrease of EGR1." (PMID 29607419, 2017). "However, some studies have indicated that EGR1 may accelerate tumor progression by stimulating cellular proliferation, invasion and angiogenesis in certain cancer types, such as prostate, ovarian, gastric and liver cancers." (PMID 33346749, 2020). "However, mechanisms responsible for the downregulation of Egr1 in liver cancer remain unknown." (PMID 29607419, 2017). "To this data, we report that the upregulated expression level of miR675, H19, HP1α, EGR1, PKM2, H-Ras were consistent in liver cancer patients and miR-675 upregulates long noncoding RNA H19 through activating EGR1 in human liver cancer cells." (PMID 26376677, 2015). "At the first time, our results showed that the expression level of miR675, H19, HP1α, EGR1, PKM2, H-Ras were consistent in 10 cases of liver cancer patients and their upregulated expression rate added up to 100% (liver cancer tissue vs paracancerous liver tissue)." (PMID 26376677, 2015).
myeloma (14 papers, 2012 to 2025). "In contrast, another patient with an NTRK1 fusion, MMRF 2490, had clonal mutations in well-known myeloma tumor suppressors EGR1 and DIS3, meaning that targeting the NTRK1 fusion alone may not have been sufficient." (PMID 32471990, 2020). "YTHDF2 is also highly expressed in multiple myeloma (MM), where it promotes proliferation through m6A-dependent degradation of EGR1 mRNA, thereby disrupting the EGR1/p21cip1/waf1/CDK2–Cyclin E1 axis." (PMID 40973767, 2025). "To test if FGF23 activates signaling in myeloma cells, we assessed EGR1, an early response transcription factor induced by FGF23 in kidney tubules." (PMID 25944690, 2015). "EGR1 (early growth response protein 1) is characterized as a tumor suppressor in multiple myeloma." (PMID 37065484, 2023). "Interestingly improved outcome for the bortezomib treatment is associated with increased JUN or Egr1 expression, while JUN or EGR1 knockdown increases the resistance of myeloma cells against bortezomib." (PMID 35923847, 2022). "In multiple myeloma cells, JUN overexpression induces cell death and growth inhibition by upregulation of the EGR1, which in turn downregulates Survivin and triggers caspase signaling." (PMID 35923847, 2022). "In multiple myeloma, EGR1 that is induced by JUN triggers the EGR1–survivin–caspase signaling cascade and drives tumor cell apoptosis." (PMID 33842351, 2021). "EGR1 has been demonstrated to be a tumor suppressor involved in hematological malignancies such as AML, CML, multiple myeloma, and B cell lymphoma." (PMID 32260160, 2020). "In agreement with the gene model, compared with bortezomib-sensitive myeloma cell lines (negative control), there was an increase in mRNA expression of SCN9A, RGS7, NTF3, HSPB8, and ZBED1 and a decrease in CCND1, COBLL1, EGR1, OCLN, and ZBED1 mRNA expression of bortezomib-resistant cell lines." (PMID 36467498, 2022). "In conclusion, a total of 393 DEGs were identified between osteocytes co-cultured with and without myeloma cells, and KLF4, IRF8, EGF, EGR1, S1PR1, C3AR1, and NPY1R might be involved in osteocyte cell apoptosis induced by MM cells." (PMID 27405725, 2016).
breast tumor (12 papers, 2013 to 2024). "In human ER+ breast tumors treated with endocrine therapy, higher EGR1 expression was associated with a more favorable prognosis." (PMID 29228577, 2017). "To determine whether EGR1 expression was associated with disease free survival, we used publicly available gene expression datasets for ER+ human breast tumors treated with endocrine therapy (adjuvant tamoxifen or AI as the only systemic therapy)." (PMID 29228577, 2017). "Among them, Early growth response 1 (EGR1) is an “immediate early” transcription factor that plays an important role in the migration of breast tumors." (PMID 39308866, 2024). "In this study we show for the first time that the putative breast tumor suppressor gene CST6 is consistently repressed by the oncogenic transcription factor TBX2 through a mechanism involving EGR1." (PMID 24742492, 2014). "For instance, DMOCPTL (a derivative of natural product parthenolide) binds to glutathione peroxidase 4 (GPX4), upregulating early growth response 1 (EGR1) and inducing mitochondrial-mediated apoptosis, effectively inhibiting breast tumor growth." (PMID 39664391, 2024). "In CD11b+ MDSC infiltrating 4T1 breast tumors (group 3), HIF1A, EGR1, NF-kappaB1 and c-jun are the transcription factors with the highest z-scores (HIF1A, EGR1, NF-kappaB1, c-jun)." (PMID 25294811, 2014). "Therefore, suppression of EGR-1 and CYP19 aromatase expression by dietary chrysoeriol in the breast tumor microenvironment may be beneficial as a preventive agent or as a chemotherapeutic adjuvant against estrogen receptor-positive breast cancer." (PMID 33053908, 2020).
osteosarcoma (12 papers, 2011 to 2022). A usually aggressive malignant bone-forming mesenchymal neoplasm, predominantly affecting adolescents and young adults. "Upregulation of EGR1 in QPD megakaryocytes is interesting as EGR1 has been implicated in the regulation of PLAU in osteosarcomas." (PMID 28301587, 2017). "Subsequent ChIP assay showed that the chromatin fragment corresponding to the assumed EGR1 binding site (BS1) was specific in anti‐EGR1 immunoprecipitate of osteosarcoma cells, and the binding was enhanced after treatment with Scutellarin." (PMID 34346162, 2021). "An increasing amount of evidences have shown that EGR1 is involved in osteosarcoma development and progression, particularly as a tumour suppressor." (PMID 34346162, 2021). "Taken together, these results suggest that EGR1/Linc00857/miR‐105‐5p/c‐Myc signal axis plays an essential role in antitumour effects of Scutellarin on osteosarcoma." (PMID 34346162, 2021). "Increased EGR1 enhanced tumour‐suppressive effects of Scutellarin on osteosarcoma cells via transcriptionally downregulating LINC00857 expression." (PMID 34346162, 2021). "Collectively, these results indicate that EGR1 plays a pivotal role in anticancer effects of Scutellarin in osteosarcoma cells." (PMID 34346162, 2021). "Taken together, these results suggest that EGR1 is increased under Scutellarin treatment in osteosarcoma." (PMID 34346162, 2021). "Mechanistically, we uncovered that Scutellarin induced EGR1 increase in osteosarcoma cells, which led to cell apoptosis increase and cell growth decrease." (PMID 34346162, 2021). "In this study, we found that Scutellarin inhibited the proliferation and induced apoptosis of osteosarcoma cells by upregulating the expression of EGR1." (PMID 34346162, 2021). "In conclusion, ML264 inhibited the JAK2/STAT3 and Wnt/β‐catenin signalling pathways via down‐regulation of KLF5 and EGR1 expression, thereby inhibiting proliferation and metastasis of osteosarcoma cells." (PMID 32285603, 2020). "In our study, the expression of EGR1 was higher in metastatic osteosarcoma tissues than primary tissues, but its role in osteosarcoma remained unclear." (PMID 32974202, 2020). "The integrated bioinformatics analysis was utilized to provide new insight into osteosarcoma development and metastasis and identified EGR1, CXCL10, MYC, and CXCR4 as potential biomarkers for prognosis of osteosarcoma." (PMID 32974202, 2020). "It was also discovered that LPA elevated Egr-1 levels via LPA receptor mediated MAPK activation in human osteosarcoma MG-63 cells." (PMID 31906413, 2020). "Experiments show that the strong expression of EGR1 can prevent osteosarcoma cells from migrating into blood vessels, thus inhibiting osteosarcoma to a certain extent." (PMID 30936265, 2019). "The increased expression of the transcriptional regulator EGR1 in QPD megakaryocytes is interesting as EGR1 is involved in the regulation of uPA, and overexpression of EGR1 has been shown to down-regulate uPA and uPAR in osteosarcomas." (PMID 28301587, 2017). "Here, we report that expression of EGR1 is down-regulated in human osteosarcoma cell lines and patient’ biopsy specimens." (PMID 21283769, 2011). "Real-time PCR was performed to examine the gene expression of EGR1 in osteoblast and osteosarcoma cell lines including NHOst, 143B, Saos-2, HOS, MG63, and NOS-1." (PMID 21283769, 2011). "ELISA showed that forced expression of EGR1 in osteosarcoma cell lines down-regulated the activity of uPA." (PMID 21283769, 2011). "Significantly lower proportions of 143B, Saos-2, and HOS cells transiently transfected with EGR1 expression vector migrated through matrigel-coated chambers than osteosarcoma cells transfected with control vector." (PMID 21283769, 2011). "To examine the expression of EGR1 following low-dose chemotherapy in vivo, we used a novel osteosarcoma murine xenograft model with 143B cells." (PMID 21283769, 2011).